PTPRG (protein tyrosine phosphatase receptor type G)
Description:
Possesses tyrosine phosphatase activity.
Synonyms: R-PTP-gamma; PTPG; RPTPG; HPTPG
Tractability: Small molecule: a structure with a bound ligand is known; it belongs to a druggable protein family. Antibody: its Gene Ontology location is reachable by antibodies, with high confidence; UniProt predicts a signal peptide or a membrane-spanning region; the Human Protein Atlas places it where antibodies can reach. PROTAC: ubiquitination databases record sites on it; its protein half-life has been measured; a small molecule that binds it is known.
Target class: Enzyme; Protein Phosphatase; Receptor tyrosine-protein phosphatase; Tyrosine protein phosphatase; Phosphatase
Gene: Protein-coding gene on chromosome 3 (61,561,569 to 62,297,609, forward strand). Ensembl gene ENSG00000144724.
Subcellular location: Membrane
Subcellular location (Human Protein Atlas): Plasma membrane
Gene Ontology:
Molecular function: identical protein binding; protein binding; protein tyrosine phosphatase activity; transmembrane receptor protein tyrosine phosphatase activity
Biological process: negative regulation of epithelial cell migration; regulation of homophilic cell adhesion; cell surface receptor protein tyrosine kinase signaling pathway; neuron projection development; signal transduction; negative regulation of neuron projection development
Cellular component: extracellular exosome; plasma membrane; extracellular region; membrane
Genetic constraint (gnomAD): Loss-of-function variants: 83 observed, 139.6 expected, observed/expected ratio (o/e) 0.59, 90% interval 0.5 to 0.71. The upper end of that interval is the gene's LOEUF score, 0.71, which puts it in group 2 of 6, group 1 being the genes least tolerant of losing a copy. Missense variants: 1,723 observed, 1,774.3 expected, observed/expected ratio (o/e) 0.97, 90% interval 0.93 to 1.01. Synonymous variants: 632 observed, 651.06 expected, observed/expected ratio (o/e) 0.97, 90% interval 0.91 to 1.04.
Homologues: Orthologues: chimpanzee PTPRG (99% identical), macaque PTPRG (99% identical), rabbit PTPRG (96% identical), dog PTPRG (95% identical), rat Ptprg (95% identical), mouse Ptprg (94% identical), guinea pig PTPRG (94% identical), pig PTPRG (92% identical), tropical clawed frog ptprg (79% identical), zebrafish ptprga (72% identical). Paralogues in human: PTPRZ1 (49% identical), PTPRS (27% identical), PTPRD (27% identical), PTPRF (26% identical), PTPRM (21% identical), PTPRK (21% identical), PTPRU (21% identical), PTPRT (20% identical), PTPRC (18% identical), PTPRA (17% identical), PTPRE (16% identical), PTPRB (16% identical), and 23 more.
Diseases named in the same sentence as PTPRG in open-access papers:
PTPRG is named in the same sentence as 71 diseases in open-access papers, as found by Europe PMC text mining. Sharing a sentence is not in itself a finding about the gene and the disease. The quoted sentences say what the papers report.
breast carcinoma (11 papers, 2011 to 2025). "Lower expression levels of PTPRG were found in breast cancer, which caused uncontrolled cell proliferation." (PMID 27602768, 2016). "The expression of PTPRG is reduced during breast carcinogenesis and is particularly low in high malignancy grade breast cancer." (PMID 39034460, 2024). "In breast cancer, PTPRG was found to inhibit tumor formation, and miR-19b was validated to support cell migration by suppressing PTPRG expression." (PMID 36405010, 2022). "Because microRNAs are powerful post-transcriptional regulators of gene expression, we used bioinformatics analysis to search for microRNAs that potentially targets PTPRG in the setting of breast cancer." (PMID 27602768, 2016). "Next, we experimentally confirmed the negative regulation of PTPRG by miR-19b in breast cancer cells." (PMID 27602768, 2016). "In this study, we found an alternative mechanism in which increased miR-19b negatively regulates PTPRG expression at the post-transcriptional level in human breast cancer." (PMID 27602768, 2016). "In this study, we found that PTPRG protein levels were downregulated in breast cancer tissues while the mRNA levels varied irregularly, implying a post-transcriptional mechanism was involved." (PMID 27602768, 2016). "The correlation between miR-19b and PTRPG was further examined by assessing PTPRG expression in the human breast cancer cell line MCF-7 and MDA- 231 after overexpressing or knocking down miR-19b." (PMID 27602768, 2016). "After removing the miRNAs previously reported to be tumor suppressor or increased in breast cancer, miR- 19a and miR-19b (miR-19a/b) were finally selected as candidate regulatory miRNAs of PTPRG." (PMID 27602768, 2016). "Because PTPRG reduction can mimic miR-19b induction in promoting breast cancer cell proliferation and migration and suppressing apoptosis, it is possible that targeting PTPRG is one mechanism by which miR-19b exerts its oncogenic function." (PMID 27602768, 2016). "In agreement with this, miR-19b was found herein to directly suppress PTPRG expression and consequently promote cell proliferation and migration and inhibits the apoptosis of breast cancer cells." (PMID 27602768, 2016). "Taken together, our findings provide the first evidence that miR-19b inhibits PTPRG expression to promote tumorigenesis in human breast cancer." (PMID 27602768, 2016). "Recently, a member of the PTP family, PTPRG, has emerged as an estrogen-regulated tumor suppressor gene in human breast cancer." (PMID 27602768, 2016). "This disparity between the protein and the mRNA PTPRG expression in human breast cancer suggests that a post-transcriptional mechanism is involved in the regulation of PTPRG." (PMID 27602768, 2016). "Taken together, this study provides the first evidence that miR-19b reduces PTPRG expression at the post-transcriptional level to promote tumorigenesis in human breast cancer." (PMID 27602768, 2016). "In recent decades, reduced expression of PTPRG has been frequently reported in multiple cancers, such as lung cancer, ovarian cancer and breast cancer." (PMID 27602768, 2016). "The data indicated that miR-19b mediates the post-transcriptional repression of PTPRG gene expression in human breast cancer." (PMID 27602768, 2016). "Previous studies showed PTPRG is involved in regulation of the ERK1/2 signaling pathway in breast cancer cells and also cyclinD1/Rb in NPC." (PMID 25970784, 2015). "Over-expression of PTPRG in breast cancer cells prolongs doubling times and colony sizes of breast cancer cells and inhibits in vivo breast tumor formation through up-regulation of p21 and p27 by suppression of ERK1/2." (PMID 25970784, 2015). "In MCF-7 breast cancer cells, PTPRG inhibits proliferation and anchorage-independent growth and reduces tumor formation in a xenograft model." (PMID 22118688, 2011).
breast carcinoma (continued). "A tumor suppressive function of PTPRG has been reported in breast cancer and PTPRG was one of the earliest suggested oral cancer genes but has not been reported as lost in recent CGH studies." (PMID 21386901, 2011). "PTPRG is a receptor-type PTP implicated as a candidate tumor suppressor gene in several types of tumors, including breast cancer." (PMID 22118688, 2011). "However, PTPRG has been postulated as a tumor suppressor in breast cancer cells because its expression is decreased in breast tumor tissues, and its overexpression inhibits anchorage-independent growth and proliferation of breast cancer cells." (PMID 28717188, 2017). "In this study, we identified a novel relationship between miR-19b and PTPRG in human breast cancer." (PMID 27602768, 2016). "Because PTPRG is an important tumor suppressor that is frequently deleted in multiple tumors, it may be a potential new target for breast cancer therapy." (PMID 27602768, 2016). "Although decreased PTPRG expression and increased miR-19b expression play important regulatory roles in carcinogenesis, little is known about the correlation between miR-19b and PTPRG in breast cancer." (PMID 27602768, 2016). "Furthermore, we detected an inverse correlation between miR-19b and PTPRG expression in breast cancer tissues." (PMID 27602768, 2016). "First, we determined the expression patterns of PTPRG in human breast cancer tissues." (PMID 27602768, 2016). "Finally, the biological roles of the miR-19b-mediated inhibition of PTPRG expression in human breast cancer were investigated." (PMID 27602768, 2016). "Interestingly, a previous study of PTPRG in breast cancer also confirmed that PTPRG regulates the ERK1/2 pathway, which is also one of the key EGFR-regulated signaling pathways." (PMID 25970784, 2015). "In addition PTPRG has been identified as a tumor suppressor gene in breast cancer." (PMID 39034460, 2024). "Therefore, modulation of PTPRG by miR-19b may explain, at least in part, why the upregulation of miR-19b can promote tumor growth and breast cancer formation." (PMID 27602768, 2016). "For instance, four of the most survival-related experimentally validated genes are on the top of our discovered genes weights list, including PTPRG, MYST1, BG683264, and AK094562 for the breast cancer gene expression dataset." (PMID 33981841, 2021). "Thus, miRNAs may be a biologically relevant regulator of PTPRG expression in human breast cancer." (PMID 27602768, 2016). "PTPRG is involved in the control of FGFR1 activity and influences the sensitivity of sarcoma cells to FGFR kinase inhibitors, and is important for cytostasis in breast cancer." (PMID 39034460, 2024). "We further identified an inverse correlation between miR-19b and PTPRG protein levels, but not mRNA levels, in human breast cancer tissues." (PMID 27602768, 2016). "Thus, PTPRG was deduced to be a miR-19b target based on both computational predictions and the inverse correlation between the levels of miR-19b and PTPRG protein, but not mRNA levels, in human breast cancer." (PMID 27602768, 2016). "After measuring the protein levels of PTPRG in 14 paired breast cancer tissues and their corresponding noncancerous tissues, we observed that the PTPRG protein levels were dramatically reduced in the breast cancer tissues compared with the noncancerous tissues." (PMID 27602768, 2016). "However, the mechanism of PTPRG silencing in breast cancer is not clear." (PMID 27602768, 2016).
chronic myeloid leukemia (7 papers, 2017 to 2025). "This study concerns the analysis of the modulation of Chronic Myeloid Leukemia (CML) cell model K562 transcriptome following transfection with the tumor suppressor gene encoding for Protein Tyrosine Phosphatase Receptor Type G (PTPRG) and treatment with the tyrosine kinase inhibitor (TKI) Imatinib." (PMID 36077295, 2022). "In chronic myeloid leukemia, PTPRG hypermethylation drives resistance to tyrosine‐kinase inhibitors, underscoring its role in constraining aberrant growth signals." (PMID 41050668, 2025). "Protein tyrosine phosphatase receptor gamma (PTPRG) expression is a natural inhibitory mechanism that is downregulated in chronic myeloid leukemia (CML) disease." (PMID 32700424, 2020). "We have previously demonstrated that methylation-driven downregulation of PTPRG expression occurs in chronic myeloid leukemia (CML)." (PMID 28637510, 2017). "Notably, in chronic myeloid leukemia (CML), PTPRG is significantly downregulated in leukemic cells at diagnosis, and PTPRG hypermethylation has been identified as an independent mechanism of resistance to tyrosine kinase inhibitor therapy." (PMID 41050668, 2025). "Additionally, PTPRG was also found to suppress the progression of tumors not only in solid tumors but also in chronic myeloid leukemia." (PMID 36405010, 2022).
Alzheimer disease (6 papers, 2022 to 2025). A progressive, neurodegenerative disease characterized by loss of function and death of nerve cells in several areas of the brain leading to loss of cognitive function such as memory and language. "Likewise, PTPRG has been associated with Alzheimer’s disease (AD), one of the most frequent forms of dementia in the world." (PMID 35053232, 2022). "In 5XFAD Alzheimer’s disease mouse model, astrocytes surrounding the β-amyloid plaques are highly positive for PTPRG expression, suggesting as a possible factor for astrocytic activation during neuroinflammation." (PMID 35053232, 2022). "PTPRG may also play a role in microglia-neuron crosstalk in Alzheimer’s disease progression." (PMID 41333442, 2025).
glioblastoma (5 papers, 2016 to 2021). The most malignant astrocytic tumor (WHO grade IV). "In the present study, we examined whether the R5 RPTP subfamily members PTPRZ and PTPRG are associated with glioma stemness and tumorigenicity in rat C6 and human U251 glioblastoma cells using gene silencing." (PMID 28717188, 2017). "Noteworthy, in Central Nervous System (CNS) PTPRZ/PTPRG appears to be crucial in maintaining glioblastoma cell-related neuronal stemness, carving out a pathological functional role also in this tissue." (PMID 35071225, 2021). "Here, by western blotting, we confirmed specificity of TPγ B9-2 in a glioblastoma cell line DBTRG overexpressing endogenous PTPRG." (PMID 28637510, 2017). "In the present study, we demonstrated that PTPRZ and its family member PTPRG play critical roles in maintaining the stem cell-like properties of glioblastoma cell lines." (PMID 28717188, 2017). "Despite the fact that it has been clarified a suppressive role for PTPRG in various tumors, limited data suggesting an oncogenic role by the receptors PTPRZ/PTPRG in glioblastoma." (PMID 35071225, 2021). "As NAZ2329 preferentially inhibits both PTPRG and PTPRZ1, NAZ2329 is expected to be superior to sole inhibitors of PTPRZ or PTPRG for inhibiting the malignant properties of glioblastoma cells." (PMID 28717188, 2017). "Tumor-relevant levels of 2-HG were added for 48 h to U-251 MG (IDH1 wild type) glioblastoma cells and potential changes in DUSP16, PTPRG and PTPRT expression levels were monitored." (PMID 27586084, 2016).
nasopharyngeal carcinoma (5 papers, 2009 to 2022). A carcinoma arising from the nasopharyngeal epithelium. "Inactive forms or total loss of PTPRG protein have been described in sporadic and Lynch syndrome colorectal cancer, nasopharyngeal carcinoma, ovarian, breast, and lung cancers, gastric cancer or diseases affecting the hematopoietic compartment as Lymphoma and Leukemia." (PMID 35071225, 2021). "In nasopharyngeal carcinoma, PTPRG inhibited the Akt signaling pathway mediating growth and invasion of cancer cells." (PMID 36405010, 2022). "A few studies addressed the role of PTPRG in nasopharyngeal carcinoma, where the extracellular matrix (ECM) seems to play a key role in cell-cycle progression." (PMID 35071225, 2021). "An important tumor suppressor gene, PTPRG is frequently deleted in breast, nasopharyngeal carcinoma and renal cell cancers." (PMID 34389752, 2021). "Protein Tyrosine Phosphatase, Receptor Type G (PTPRG) was identified as a candidate tumor suppressor gene in nasopharyngeal carcinoma (NPC)." (PMID 25970784, 2015).
schizophrenia (5 papers, 2018 to 2026). A major psychotic disorder characterized by abnormalities in the perception or expression of reality. "For instance, PTPRG (cg00974944) and PCDH1 (cg10365572), both associated with the maternal schizophrenia PGS, are involved in cell growth regulation and neural adhesion, respectively, supporting the role of dysregulated synaptic processes in schizophrenia risk." (PMID 40181191, 2025). "Finally, a large exome sequencing study disclosed four schizophrenia patients that each carried a de novo missense mutation in a different PTP gene; either in PTPN3 or in one of the three receptor-type PTP genes PTPRF, PTPRG and PTPRJ." (PMID 36755664, 2022).
colorectal cancer (3 papers, 2016 to 2021). A primary or metastatic malignant neoplasm that affects the colon or rectum. "Previous studies on the mutational analysis of the tyrosine phosphatase gene superfamily in human cancers identified 83 somatic mutations in six PTPs (PTPRF, PTPRG, PTPRT, PTPN3, PTPN13, PTPN14), affecting 26% of colorectal cancers and a smaller fraction of lung, breast and gastric cancers." (PMID 27833130, 2016).
diabetes (3 papers, 2020 to 2024). "Protein Tyrosine Phosphatase Receptor-type Gamma (PTPRG), identified as a tumor suppressor gene, has been demonstrated to play a role in metabolic disorders such as diabetes." (PMID 39408856, 2024). "Although the distinctive feature of PTPRG is that of TS in many forms of cancer, it also participates in other pathological processes such as liver inflammation, diabetes, and neuropsychiatric/behavioral disorders." (PMID 35053232, 2022). "For instance, the hepatic expression of PTPRG is known to be upregulated in response to inflammation in obese and type 2 diabetes mellitus (T2DM) mouse models, aligning with findings in humans where elevated PTPRG expression positively correlates with markers of inflammation and insulin resistance." (PMID 39408856, 2024).
lung adenocarcinoma (3 papers, 2019 to 2021). A carcinoma that arises from the lung and is characterized by the presence of malignant glandular epithelial cells. "However, up‐regulation of circ‐cMras suppressed lung adenocarcinoma tumorigenesis by targeting miR‐567/PTPRG signalling, suggesting the oncogenic function of miR‐567 in lung adenocarcinoma." (PMID 33675150, 2021).
Obesity (3 papers, 2021 to 2025). Accumulation of substantial excess body fat. "Instead, in humans, liver PTPRG overexpression appears to correlate with inflammatory mechanisms and obesity." (PMID 35053232, 2022).
sarcoma (3 papers, 2019 to 2024). A usually aggressive malignant neoplasm of the soft tissue or bone. "Interestingly in U2OS sarcoma cells, PTPRG directly dephosphorylates the active FGFR1, connecting for the first time PTPRG to the development of sarcomas." (PMID 35071225, 2021). "Along the same line, a recent paper using a proteomic strategy identified another protein, Protein Tyrosine Phosphatase Receptor Type G (PTPRG), to be involved in controlling FGFR1 activity and influences sensitivity of sarcoma cells to FGFR kinase inhibitors." (PMID 31137681, 2019).
alcohol dependence (2 papers, 2018 to 2023). Physical and psychological dependence on alcohol. "A GWAS study in 3,838 individuals of European- and African- American ancestry reported that the activities of PTPRG were associated with alcohol dependence." (PMID 37875790, 2023). "Another PTPR family member, PTPRG, does not produce significant associations on its own with addiction-related phenotypes, but significant epistatic interactions of PTPRG markers with other genes were found in a recent GWAS examining alcohol dependence symptom counts." (PMID 29675039, 2018).
Astrocytoma (2 papers, 2021 to 2024). "Astrocytoma cell line U373-MG and primary astrocytes express PTPRG whose expression was found to be regulated by IL-1 or TNFα." (PMID 35071225, 2021). "So far, pro-inflammatory factors such as LPS or IL-1β and TNFα were reported to upregulate PTPRG in astrocytoma cell line or astrocyte culture and also appear to associate to specific myeloid lineages, such as the differentiation of monocytes to dendritic cells." (PMID 35071225, 2021). "Analysis of formalin-fixed paraffin-embedded human tissues showed overexpression of PTPRG in astrocytoma cases with no or limited expression in their healthy counterparts." (PMID 35071225, 2021).
glioma (2 papers, 2016 to 2025). A benign or malignant brain and spinal cord tumor that arises from glial cells (astrocytes, oligodendrocytes, ependymal cells). "RNAseq data from WT or IDH1 R132H-containing glioma xenografts E434 and E478 also do not point to an IDH-mutation associated difference in expression for DUSP16, PTPRG and PTPRT (WPJL, unpublished data)." (PMID 27586084, 2016).